RB1 (RB transcriptional corepressor 1)
Diseases named in the same sentence as RB1 in open-access papers (continued):
Sharing a sentence is not in itself a finding about the gene and the disease.
lung carcinoma (continued). "Furthermore, TCGA proteomic database analysis revealed that stathmin was the top 5 ranked protein whose expression is negatively correlated with the RB1 protein level in lung cancer clinical samples." (PMID 33037191, 2020). "In order to identify RB1 synthetic lethal targets, we conducted chemical and genetic vulnerability screenings using epigenetics-focused small molecules and RNAi libraries in RB1-isogenic lung cancer cells." (PMID 33037191, 2020). "RB1 expression was mostly associated with a wild-type (wt) exon mutation status and its functionality in YAP1-positive cell lines was suggested by decreased or absent CDKN2A/2B expression, previously shown as an alternate mechanism to disable the RB1 pathway in lung cancer." (PMID 29088741, 2017). "Despite the small numbers in these rare lung cancer subtypes, SNV calling using the OncoMap database revealed previously undescribed SNV in FGFR1, CDKN2A, RB1, JAK3, and CTNNB1 for the large-cell type, a BRAF mutation for carcinoid, and an AKT1 mutation for adenosquamous carcinoma." (PMID 26076459, 2015). "Its ten hub genes were extracted and confirmed in the literature; seven of them (UBC, SRC, SP1, MYC, STAT3, RB1, and MAPK1) were verified to be associated with lung cancer, while the remaining three genes, JUN, NR3C1, and GRB2, were potentially new candidate lung adenocarcinoma-related genes." (PMID 26402252, 2015). "Additionally, recent findings in lung cancer have found that RB1 and p16/CDKN2A are activated by trametinib, and have implicated RB status in sensitivity to MEK inhibitors in KRAS mutant lung cancer cells; however, the underlying processes responsible for this observation remain poorly understood." (PMID 36418460, 2022). "Among patients, frame shift insertion/deletion of ATR and the major mutation of RB1 (RB1 p.F739L) and TCF7L2 (TCF7L2 p.I271N) changed the protein structure during simulation, suggesting that they might play an important role in the development of lung cancer." (PMID 34970478, 2021). "However, considering that the CyclinD1-CDK4/6-Rb pathway is downstream of the EGFR signaling pathway, it is likely that this cell cycle pathway, which involves CDKN2B and RB1, plays an important role in lung cancer progression and/or therapeutic resistance in patients with EGFR active mutation." (PMID 29343775, 2018). "Furthermore, the tumor suppressor protein RB1 is downregulated in lung cancer and may inhibit SUV39H1." (PMID 24564251, 2013). "Consequently, the high expression of E2F1 and E2F2, alongside RB1 inactivation and activation of downstream oncogenes, constitutes a complex regulatory network that significantly influences the onset, progression, and prognosis of lung cancer, particularly NSCLC." (PMID 40568194, 2025). "In in vivo and in vitro studies, Rb1/PPD NPs exhibited the EPR effect of NPs and the synergistic effect of Rb1/PPD, resulting in a superior anti-lung cancer effect and adequate safety." (PMID 37280646, 2023).
lung carcinoma (continued). "In order to screen for RB1 synthetic lethal targets, we first generated RB1 knockout (RB1−/−) cell lines from the RB1 wildtype A549 and HCC827 lung cancer cells using a CRISPR/Cas9 system." (PMID 33037191, 2020). "Similar to other types of lung cancer, amplifications or deletions of genes in the cell-cycle pathway (CCND1, CDKN2A, and RB1) were frequently identified in PSC." (PMID 32985499, 2020). "This study identified the hyper-vulnerability of RB1-deficient cells to AURKA inhibition, and mechanistically explored the synthetic lethal crosstalk between RB1 and AURKA pathways in lung cancer cells." (PMID 33037191, 2020). "Especially, the identified genes EGFR, CDKN2A, ERBB2, RB1, and CDK4 were significantly enriched for non‐small cell lung cancer, demonstrating that UniCovEx accurately identified the cancer‐related gene modules." (PMID 30828525, 2019). "In this study, transcriptome profiling and RT-qPCR validation revealed that PGL arrests the cell cycle via downregulation of the expression of RB1, CCNH, MDM2, ACCN4, CCND2, GADD45A, and GADD45B in lung cancer cells." (PMID 27355352, 2016). "Reports describe that knockdown of ncRNA-RB1 in A549 lung carcinoma cells reduced CRT transcription without affecting RB1 protein expression." (PMID 40429961, 2025). "Moreover, the upregulation of miR-205-5p has been shown to contribute to lung cancer cell proliferation and metastasis by regulating TP53INP1, RB1, and P21." (PMID 39451748, 2024). "Moreover, NFYC-AS1 levels were sufficient to discriminate between RB1-wt and RB1-mut NSCLC tumors and lung cancer cell lines, with good levels of accuracy." (PMID 38467619, 2024). "Similar enrichments of SGMs were seen in other core TSGs such as RB1, NF1, and ARID1A and emerging TSGs such as MGA, a transcription factor of the MYC network that suppresses growth and invasion in cellular and mouse models of lung cancer." (PMID 37922356, 2023). "For example, in mice bearing RB1 null lung cancer, upregulation of glucose transporter (GLUT) 1 and two rate-limiting enzymes in glycolysis, hexokinase-2 (HK2) and pyruvate kinase isozymes 2, was observed, suggesting that RB1 regulates glucose metabolism." (PMID 33627136, 2021). "Indeed, a strong negative correlation was observed between the protein levels of RB1 and STMN1 in a panel of human lung cancer cell lines and a large panel of lung adenocarcinoma (LUAD) patient samples in TCGA datasets." (PMID 34050264, 2021). "While we were generating RB1-KO lung cancer clones, we have constantly observed that α-tubulin protein level was reduced when RB1 expression was absent or reduced in lung cancer cells." (PMID 33037191, 2020).
lung carcinoma (continued). "RB1 was directly targeted by miR-661 and could interact with E2F1 to affect EMT process and invasion lung cancer." (PMID 28716024, 2017). "Hence, we examined the impact of BRG1 knockdown via an shRNA approach in 3 lung cancer- derived cell lines (H358, SK-LU-1 and HCC-827) to determine the potential effects on RB1 phosphorylation." (PMID 28105458, 2016). "In NSCLC tissues, many onco-miRs/tumor suppressor-target or tumor suppressor-miRs/onco-target pathways have been demonstrated to participate in the tumorigenesis of lung cancer, including miR7/BCL2 axis, miR-99b/FGFR3 axis, miR-101/EZH2 axis, miR-192/RB1 axis and miR-196/HOXA5 axis." (PMID 25012722, 2014). "In NSCLC, miR-93 expression was significantly correlated with survival rate, and silencing miR-93 expression might inhibit cell proliferation, migration, and invasion of lung cancer cells by targeting gene of phosphate and tension homology deleted on chromosome ten (PTEN) and retinoblastoma 1 (RB1)." (PMID 32426273, 2020). "In this study, expressions of p16INK4 RB1, and CDKN2A copy number variances (CNV) in the tumor cells were assessed by immunohistochemistry and fluorescence in situ hybridization (FISH), respectively, in 73 nonsmall cell lung cancer (NSCLC) with known 5-year survivals." (PMID 22619677, 2012). "Additionally, downregulation of RB1 in lung cancer is not able to repress TFDP1 activity, and therefore, in lung cancer, tumorigenesis is mediated through upregulation of E2F6 and TFDP1." (PMID 24564251, 2013).
small cell lung carcinoma (128 papers, 2006 to 2026). Small cell lung cancer (SCLC) is a highly aggressive malignant neoplasm, accounting for 10-15% of lung cancer cases, characterized byrapid growth, and early metastasis. "RB1 gene mutations are generally rare but reach 90% in the highly aggressive small cell lung cancer (SCLC) histotype, where they drive tumor cell hyperproliferation and increased lineage plasticity towards a neuroendocrine phenotype." (PMID 38467619, 2024). "A previous study has reported that RB1 loss is correlated with poor prognosis in glioblastoma and small cell lung cancer." (PMID 35299734, 2022). "Yet it is RB1 loss that is a nearly universal feature of human high grade neuroendocrine lung cancers like small cell lung cancer." (PMID 35368709, 2022). "Among the 63 patients who progressed from A+T regimen, three patients were detected with RB1 mutation wherein two patients (67%) were confirmed with histological transformation to small-cell lung cancer (SCLC)." (PMID 34663309, 2021). "In small-cell lung cancer, the mechanism has been shown that at least one allele of RB1 was affected by different genomic alterations (i.e., hemizygous deletion, loss of heterozygosity, or mutation, including rearrangements)." (PMID 32556556, 2021). "Our study focused on RB1 mutation in locally advanced and advanced non small cell lung cancer to better facilitate comparisons with small cell lung cancer (SCLC)." (PMID 30773851, 2019). "Common enriched mutations and cancer tissue types found across these examples include BRAF and RB1 mutations as well as skin, small-cell lung cancer, lymphoma, and leukaemia tissue types, respectively." (PMID 31602313, 2019). "Our group previously published on the genomics of small cell lung cancer and identified retinoblastoma (RB1) gene mutation status through targeted exome sequencing as a predictor of outcomes." (PMID 30773851, 2019). "Cancer genome sequencing confirmed that RB1 is mutated in a variety of cancers, including small-cell lung cancers." (PMID 29443735, 2018). "Among small-cell lung cancers, frequent mutations are seen in retinoblastoma 1 (RB1), E1A-binding protein p300 (EP300), MLL2, and PIK3CA." (PMID 26970967, 2016). "Small cell lung cancers (SCLC) have often inactivating mutations in RB1." (PMID 37739954, 2023).
small cell lung carcinoma (continued). "Interestingly, two recent studies carried out in RB-deficient small cell lung cancer cells and triple-negative breast cancer cells have shown that Aurora A or B kinase inhibition is synthetic lethal with loss of the RB1 tumor suppressor gene." (PMID 31366128, 2019). "Additionally, a recent genomic study in small cell lung cancer showed that presence of RB1 inactivating mutation was highly predictive of good response to platinum-based chemotherapy." (PMID 28390395, 2017). "Furthermore, EGFR-resistant lung adenocarcinoma with RB1 mutations could transform into a more aggressive small-cell lung cancer." (PMID 37020866, 2023). "Retinoblastoma 1 (RB1) alterations, when present with EGFR, have been associated with transformation into small-cell lung cancer under drug pressure, as a mechanism of acquired resistance." (PMID 40723270, 2025). "This idea has been validated clinically in small cell lung cancers that are generally insensitive to CDK4/6i due to their RB1 locus alteration, leading to recent approval by the FDA of trilaciclib for this indication." (PMID 36453028, 2024).